CASP8 (caspase 8)
Diseases named in the same sentence as CASP8 in open-access papers (continued):
Sharing a sentence is not in itself a finding about the gene and the disease.
infection (continued). "Paradoxically, lymph node mDC did not accumulate in progressive infection but rather died from caspase-8-dependent apoptosis that was reduced by ART, indicating that increased recruitment is offset by increased death." (PMID 21203477, 2010). "In vivo, selective caspase-8 inhibition produces, in the absence of other stimuli, marked neutrophilia driven by circulating proinflammatory and chemotactic cytokines and promotes bacterial clearance during infection." (PMID 42260177, 2026). "Additionally, we observed that ΔnleB/espL triggered enhanced macrophage cytotoxicity, caspase-8 and caspase-1 processing, GSDMD cleavage and IL-1β maturation compared to ΔnleB infection in LPS-primed macrophages, while ΔnleB/espL complemented with nleB or espL caused less cell lysis (Fig. EV5A)." (PMID 40128366, 2025). "It is therefore highly conceivable that the activation of caspase-6 (and presumably, subsequent caspase-8 activation) promotes the activation of caspase-3, increasing the efficiency of the caspase-3-dependent, GSDME-mediated cell lysis observed during WT EMCV infection." (PMID 39928567, 2025). "Notably, IL-6 inflammatory factor, CASP8, and APOA1 may also be the key genes with altered expression after pathogen infection, which are closely related to the inflammatory response to tracheal injury in calves." (PMID 40005807, 2025). "While 5448AP infections activated caspase-8, 5448 infections did not." (PMID 38408992, 2024). "However, CASP8 siRNA knockdown in CASP1−/− Caco-2 cells did not abrogate inflammasome activation during Δ6 Yptb infection, indicating that additional caspase activation pathways likely mediate cell death during Δ6 Yptb infection of human IECs." (PMID 37615436, 2023). "The involvement of caspases 8 and 9 was also investigated and no significant changes over time for caspase 8 were observed, while caspase 9 was cleaved starting at 24 h post-infection (a decrease in constitutive form of caspase at 48 and 72 h after infection was observed)." (PMID 38087282, 2023). "Similarly, Casp1/11+/–Casp8–/–Ripk3–/– mice retain the ability to recruit Caspase-1 to NLRC4 and to initiate cell death via Caspase-11 and should also thus be resistant to infection." (PMID 36645406, 2023). "Intriguingly, ablating Gsdmd on a Casp8–/–Ripk3–/– background did not reproduce the C. rodentium lethality phenotype as obtained after Casp1/11 deletion, as all Casp8–/–Ripk3–/–Gsdmd–/– mice survived the infection." (PMID 37080966, 2023). "While caspase 8 was not involved, caspase 9 cleavage started 24 h post-infection." (PMID 38087282, 2023). "Simultaneous knockdown of caspase-1 and caspase-8 still allowed for the release of IL-18 during Δ6 Yptb infection, suggesting that they are unlikely to play overlapping roles and may act sequentially." (PMID 37615436, 2023). "However, the levels of pro-caspase-8 were unchanged and the cleaved form of caspase-8 was never detected throughout the infection, suggesting that the infection only induced the activation of a caspase-9-dependent intrinsic apoptotic pathway." (PMID 33481814, 2021). "We examined total cell lysates collected at various time points after infection and found that anti-apoptotic Bcl-2 was downregulated at 72 hrs p.i. and survivin declined at 24 and 72 hrs p.i. in both cell line while FLIP, an inhibitor of pro-caspase-8, remained unchanged." (PMID 33481814, 2021). "Western blots showed significant activation of caspase-3, -9, -7, and poly (ADP-ribose) polymerase (PARP) (which indicated intrinsic apoptotic pathway activation), but not caspase-8 (which is involved in the extrinsic apoptotic signaling pathways), after 48 h of infection." (PMID 33424801, 2020). "The absence of vICA during ∆M36 infection allows CASP8 cleavage activation within infected cells." (PMID 33126536, 2020).
infection (continued). "We found that infection with wild type bacteria and fliI mutants (that express cytosolic flagellin, but do not assembly the flagellum), but not with flaA mutants, triggers robust CASP8 activation in Casp1/11–/–and Gsdmd–/–macrophages." (PMID 31251782, 2019). "Caspase 8 enzymatic activity negatively regulates necroptosis via RIPK1 and RIPK3 instability, and we found that type I IFNs limited caspase expression during infection, providing a potential mechanism whereby IFNα/β facilitate pathologic RIPK1-RIPK3 interaction and downstream RIPK3 activation." (PMID 30080899, 2018). "Interestingly, expression of full length CD95L slowed down the growth of the NB7 cells right after infection with the lentivirus despite the absence of caspase-8 (data not shown)." (PMID 29063830, 2017). "Together, these findings underscore the context-dependent and multifunctional roles of caspase-8 during infection, and suggest that selective inhibition of its non-apoptotic signalling might blunt cytokine production but could also predispose to increased necroptotic cell death." (PMID 41233351, 2025). "However, although caspase-8 was cleaved in TNF/SM treated macrophages and neutrophils, caspase-8 was not cleaved following PAO1 infection, indicating that there is no requirement for caspase-8 in GSDMD processing or IL-1β secretion induced by PAO1 infection of neutrophils." (PMID 37730693, 2023). "Given that during Influenza A infection ZBP1 has been shown to drive both apoptosis and necroptosis, and as our prior results suggested that VZV could not inhibit caspase 8, we tested if either or both pathways were being triggered during infection with the two mutant viruses." (PMID 32649716, 2020). "However the activity of caspase-8 was not affected by PPV infection." (PMID 26880103, 2016). "Therefore in the absence of cFLAR induction, and in conjunction with the observed TNF-α production, we hypothesize that infection in the absence of pXO1 probably induces apoptosis through a classical extrinsic TNF-α receptor-mediated caspase-8 pathway." (PMID 19014542, 2008). "Our data supports a hypothesis that in the presence of pXO1, apoptosis may proceed through the mitochondria-dependent pathway, while in the non-toxigenic infection it seems likely to be activated mainly through an extrinsic TNF-α receptor-mediated caspase-8 pathway." (PMID 19014542, 2008). "In contrast to infection with ΔospD3, infection with ΔospC1ΔospD3 did not increase the levels of phosphorylation of MLKL or cytotoxicity, whereas caspase-8 activity was elevated in cells infected with ΔospC1 or ΔospC1ΔospD3." (PMID 40931196, 2025). "As opposed to infections with large DNA viruses, IAV-mediated ZBP1 activation induces both RIPK3-RIPK1-caspase-8–dependent apoptosis and RIPK3-MLKL–mediated necroptosis." (PMID 37450010, 2023). "TNF-α plus cycloheximide (CHX) treatment triggered autocleavage of caspase-8 as well as its cleavages of Bid, caspase-3, caspase-7, and PARP1, all of which was blocked by infection with CopC-positive C. violaceum but not ΔcopC strain." (PMID 35446120, 2022). "Mice lacking caspase-8, RIPK3, and RIPK1 (apoptosis/necroptosis) survived infection similarly to mice lacking either RIPK3 or MLKL, suggesting pyroptosis primarily protects against B. thailandensis in pyroptosis-competent mice." (PMID 34154417, 2021).
infection (continued). "Contrary to these results, neither ActoD nor caspase 8 inhibition had any effect on RVB-14, in keeping with previous data showing that RVB-14 infection benefits from apoptosis induction." (PMID 34960671, 2021). "It has been shown that infection of murine macrophages with MCMV lacking both M36 and M45, and thus unable to inhibit caspase 8 and RHIM signalling, leads to a highly inflammatory cell death program involving apoptosis followed by secondary necroptosis." (PMID 32649716, 2020). "Apoptosis: Ad-infection did not increase caspase-3/7 or caspase-8 activities either in A549 or HOS cells but led to a decrease in mitocondrial membrane potential (Δψm) in A549 after 72 h of infection." (PMID 31969562, 2020). "The combined lack of caspase-8-mediated apoptosis and RIPK3-driven necroptosis did not have significant impact on Salmonella titers 3 weeks post-infection." (PMID 32735843, 2020). "Collectively, these results suggest that infection with GBS triggers, in neutrophils, pro-IL-β processing and IL-β secretion via a mechanism that largely depends on caspase-1, but not on caspase-8 or on serine proteases." (PMID 27509078, 2016). "Treatment of IAV-infected P815 cells with VAD (pan-caspase inhibitor) and LEHD (caspase-9 inhibitor) dramatically decreased viral titers 24 h after infection, and IETD (caspase-8 inhibitor) did not." (PMID 24923273, 2014). "In this study, we demonstrated that a TNF-dependent cytokine network involving M.tb-infected monocytes, but not direct infection by M.tb, down-regulates MMP-2 secretion from microglial cells via p38 MAP kinase, NFκB and caspase 8 pathways." (PMID 21569377, 2011). "Additionally, there was no cleavage of apoptotic CASP8, CASP3, or CASP7 in Aim2–/– pBMDMs following MPXV infection." (PMID 41225161, 2025). "Caspase-3, caspase-8, or pan-caspase inhibition did not alter secretion of IFN-α2, IFN-γ, MCP-1, IL-6, IL-10, IL-12p70 or IL-23, as elevated levels of these cytokines were detected in all infection conditions." (PMID 38408992, 2024). "Ripk3D333A/D333A macrophages died at the same rate as wild-type (WT) macrophages in response to TNF plus cycloheximide, TNF plus emricasan, or infection with murine cytomegalovirus (MCMV) lacking M36 and M45 to inhibit caspase-8 and RIPK3 activation, respectively." (PMID 38191748, 2024). "The results showed that the levels of p-RIPK3 and p-MLKL were significantly increased in the ZBP1 overexpression PTCs comparing with the vector control transfected cells (Vec) during PPV infection, while the expression levels of RIPK3, MLKL, and Caspase-8 did not significantly change." (PMID 39614405, 2024). "Indeed, infection with VZV, which does not express any known inhibitors of caspase-8, triggers apoptosis downstream of ZBP1 in human cells, and a wild-type HSV-1 strain induces both ZBP1-mediated apoptosis and necroptosis in mouse astrocytes." (PMID 37450010, 2023). "We however find that while Semliki Forest Virus (SFV) recruits and activates caspase-8 on mitochondria as previously published, HSV-1 is not able to do so although caspase-8 can translocate to mitochondria in an inactive pro-form later during infection." (PMID 36418547, 2023). "Similarly, caspase-8 inhibition also prevented significant differences in the final percentage of cell death at 24 h between ZBP1+/+ and ZBP1−/− derived cells following infection with HSV-1(MacIntyre) or HSV-1(F) (data not shown)." (PMID 35549723, 2022). "Interestingly, by day 7 of infection, multiple genes were elevated in young H1N1 infected lung, such as Atg5, Mapk8, Tbk1, Casp8, and Ripk1, that were not similarly expressed in response to H3N2." (PMID 34829979, 2021). "In the presence of extensive cell death after infection with ZIKV, we were unable to detect the activation of pro-caspase-8 and cleaved caspase-3, and neither did we detect substrates processed by active caspases indicating that apoptosis was not initiated in ZIKV-infected astrocytes." (PMID 33796483, 2021).
infection (continued). "Thus, during ∆M36 infection, both myeloid and non-myeloid cells die by the collaboration of TNF-dependent and virus-induced CASP8-mediated apoptotic signaling." (PMID 33126536, 2020). "Importantly, CASP8 plays a central pathogen sensing role that primes cells for apoptosis and collaborates with the TNF-signaling for the execution when vICA is absent during infection." (PMID 33126536, 2020). "Moreover, screening the network interactions among the genes involved in cell death/survival for both the LV and Lena strains showed that the canonical apoptosis pathway signals (BID, CASP8, MCL1 and NFKB) were activated upon LV infection, but not following Lena infection." (PMID 24643046, 2014). "Next, to investigate whether sustained interstitial pneumonia could be fatal during the late infection phase, we evaluated the cell death of mouse lung cells and found that the expression of critical genes involved in cell death (RIP3, RIP1, Caspase-3, Caspase-8) exhibited no change." (PMID 35617354, 2022).
bacterial infection (22 papers, 2009 to 2025). "To further define this response, we investigated the potential contribution of caspase-8 to cytokine production in response to bacterial infection and individual pathogen-associated molecular patterns (PAMPS) in bone marrow-derived macrophages (BMDMs)." (PMID 27737018, 2016). "The profound loss of anti-microbial immune defense and severe susceptibility to bacterial infection in caspase-8-deficient animals is therefore likely the result of compound defects in antimicrobial cytokine production, rather than deficient apoptosis per-se." (PMID 27737018, 2016). "Caspase-8-dependent cell death is critical for host defense, facilitating clearance of bacterial infections." (PMID 40931196, 2025). "Our study suggests that Casp8 is dispensable for homeostatic hematopoiesis in young adult mice but is essential in preventing Ripk3-mediated necroptosis during bacterial infections or inflammations." (PMID 38637559, 2024). "Different types of insults, such as viral and bacterial infections or mechanical tissue damage, are known to activate a cFLIP/Caspase-8/RIPK1–containing cell death complex." (PMID 37494451, 2023). "The significantly delayed cell death and extensive cell-cell fusion observed in B. thailandensis-infected Casp8/Ripk3/Casp1/11−/− BMDMs suggested that bacterial infection is poorly controlled in these cells compared to WT." (PMID 34154417, 2021). "Caspase-8 is a central regulator of cell fate decisions in the context of bacterial infection and inflammatory stimuli." (PMID 27737018, 2016). "In conclusion we have identified a novel negative regulatory role for CARD9 on IL-1β production in macrophages by modulating pro-IL-1β expression and caspase-8 recruitment to the inflammasome in response to bacterial infection." (PMID 27670879, 2016). "Our studies further demonstrate that caspase-8 enzymatic activity plays a previously undescribed role in ensuring optimal TLR-induced gene expression by innate cells during bacterial infection." (PMID 27737018, 2016). "Unexpectedly, we found that caspase-8 enzymatic activity regulates gene expression in response to bacterial infection as well as TLR signaling independently of apoptosis." (PMID 27737018, 2016). "Additionally, caspase-8 has been found to directly cleave gasdermin D during bacterial infection, promoting pyroptosis independently of caspase-3." (PMID 41155897, 2025). "This reduction might be beneficial for the host as caspase-8 inhibition has previously been shown to improve the outcome of bacterial infections in mice." (PMID 39362931, 2024). "Furthermore, we addressed the role of caspase-8 in inflammasome activation and pyroptosis during this bacterial infection." (PMID 36532444, 2022). "Therefore, we have identified a novel mechanism through which ZBP1–RIPK1 RHIM-mediated interactions drive not only pro-inflammatory signaling, but also rapid CASP8-mediated cell death in response to bacterial infection." (PMID 33397971, 2021). "Thus, while caspase-8 is important for maximal inflammatory gene expression in response to bacterial infection, it is dispensable for innate responses against and clearance of SeV." (PMID 27737018, 2016). "However, whether caspase-8 controls anti-bacterial immune defense by regulating cell death or control of inflammatory cytokine production, as well as how caspase-8 controls inflammatory cytokine production during bacterial infection, remain unclear." (PMID 27737018, 2016). "Moreover, it is unclear whether caspase-8 plays a cell-intrinsic role in controlling gene expression in vivo during bacterial infection." (PMID 27737018, 2016). "However, it remains unclear whether caspase-1 was also activated by caspase-8, as observed in bacterial infections, by active caspases-3/7, which were previously shown to activate NLRP3-dependent inflammation upon TLR signaling, or independent activation of the NLRP3 inflammasome." (PMID 41173854, 2025).
bacterial infection (continued). "Whereas Class2 uniquely included pathways related to bacterial infections (e.g., E. coli, Salmonella) together with actin-cytoskeleton and T-cell modules (e.g., ACTB, PFN1, RAC2, PIK3CD, CD3D/CD3G, STING1, TRADD, CASP8, BCL2, HLA-F)." (PMID 41394852, 2025). "Caspase-8 interacts with the ASC adapter and promotes ASC self-assembly during bacterial infection or sterile inflammation." (PMID 39939579, 2025). "As IL-1β secretion was unaffected by caspase-8 inhibition in both wt and nga(G330D) bacterial infection, our data suggest that neither inflammasome activation nor the regulation of IL-1β levels induced by GAS involve caspase-8 activity." (PMID 28720729, 2017). "Accordingly, caspase-9 and caspase-3 were activated in a concentration-dependent manner by bacterial infection, whereas caspase-8 was not significantly affected." (PMID 19714221, 2009). "Additionally, caspase-8 may also activate GSDMD and promote the maturation of IL1β and IL18, as observed in the context of bacterial infections." (PMID 41173854, 2025). "However, no studies so far have revealed the role of caspase-7 or caspase-8 during this bacterial infection." (PMID 36532444, 2022). "Using newly-generated mice in which caspase-8 autoprocessing is ablated (Casp8DA/DA), we now demonstrate that caspase-8 enzymatic activity, but not autoprocessing, mediates induction of inflammatory cytokines by bacterial infection and a wide variety of TLR stimuli." (PMID 27737018, 2016). "Alternatively, caspase-8 could have a cell-intrinsic effect on inflammatory gene expression, which has not previously been described in vivo during bacterial infection." (PMID 27737018, 2016). "Whether caspase-8 activity is also important for inflammatory gene expression during bacterial infection has not been investigated." (PMID 27737018, 2016).